MIR3919 (microRNA 3919)
Synonyms: hsa-mir-3919
Gene: MicroRNA gene on chromosome 3 (159,282,646 to 159,282,734, forward strand). Ensembl gene ENSG00000263634.
Homologues: Orthologues: chimpanzee MIR3919 (100% identical).